DUOX2 (dual oxidase 2)
Diseases named in the same sentence as DUOX2 in open-access papers (continued):
Sharing a sentence is not in itself a finding about the gene and the disease.
gastric cancer (3 papers, 2016 to 2021). A primary or metastatic malignant neoplasm involving the stomach. "The increased expression of DUOX2 mRNA and protein in gastric cancer was significantly associated with smoking history, that is, a higher DUOX2 expression in patients with smoking history." (PMID 26839536, 2016). "The elevated DUOX2 in the gastric cancer was significantly associated with smoking history." (PMID 26839536, 2016). "In an effort to address these limitations for disseminated stomach cancer, we developed a pre-clinical mouse model to evaluate the role of a likely biomarker, DUOX2, on the effectiveness of chemopotentiation by LD-WART." (PMID 34439340, 2021). "The tendencies for the DUOX2 positive tumors are thus considered reasonable and support a role for DUOX2 in mediating radiosensitivity to gastric cancer tumors." (PMID 34439340, 2021). "In the case of stomach cancer cells, it appears that DUOX2 upregulation at the mRNA and protein levels by NF-kB and Stat-1 is sufficient to bypass the tolerance levels." (PMID 34439340, 2021). "The mechanisms that lead to DUOX2 upregulation in gastric cancer cells probably involve NF-κB and Sta-1." (PMID 34439340, 2021). "We also detected that expression of DUOX2 protein and mRNA was significantly increased in gastric cancer." (PMID 26839536, 2016). "In this study, we investigated the levels of DUOX2 expression in precancerous and cancerous digestive tissues, namely, Barrett esophagus, gastric cancer, CRC, and hepatic carcinoma." (PMID 26839536, 2016). "Here, we investigated the expression of DUOX2 in human tumors and designed pre-clinical animal studies to determine whether DUOX2 could be used as a biomarker of chemopotentiation by LDFRT for disseminated stomach cancer." (PMID 34439340, 2021). "The high levels of DUOX2in gastric cancer were significantly associated with smoking history, while itsprotein expression levels in CRC were higher in stages II-IV than in stage I.However, the results are conflicting with regard to DUOX2 and CRC." (PMID 32453337, 2020). "Our results suggest that increased DUOX2 expression may contribute to the smoking-induced tumorigenesis of gastric cancer." (PMID 26839536, 2016). "Our result suggests that DUOX2 might be involved in the carcinogenesis and development of Barrett esophagus, gastric cancer, and CRC via overproducing ROS, but the exact mechanism was unknown." (PMID 26839536, 2016). "Accordingly, the Human Protein ATLAS indicates that expression of DUOX2 is not a prognostic factor in stomach cancer." (PMID 34439340, 2021). "In order to evaluate the role of DUOX2 in chemopotentiation by LDFRT in a pre-clinical model, we first confirmed that LDFRT and the combined regimen resulted in DUOX2 upregulation in human stomach cancer cells." (PMID 34439340, 2021). "The DUOX2 mRNA and protein levels in the gastric cancer and CRC were increased compared to the adjacent nonmalignant tissues." (PMID 26839536, 2016). "The result showed that DUOX2 protein expression was increased in Barrett's esophagus, gastric cancer, and CRC compared to the corresponding nonlesion tissues." (PMID 26839536, 2016). "The reason for the variability of DUOX2 expression in human stomach cancer is not known but may be based on the levels of inflammation." (PMID 34439340, 2021). "Furthermore, DUOX2 mRNA and protein levels were significantly elevated in gastric cancer in patients with smoking history compared to those without smoking history." (PMID 26839536, 2016). "Although DUOX2 mRNA was expressed at low levels in adjacent nontumorous tissues, the DOUX2 mRNA in gastric cancer was increased 3.9-fold compared to adjacent nonmalignant control." (PMID 26839536, 2016).
gastric tumor (3 papers, 2016 to 2021). "Among other NOX family members, expression of Nox2, Duox1 and Duox2 was increased significantly in mouse gastric tumors; however, only Duox2 showed gastritis-associated induction." (PMID 30700829, 2019). "In an effort to investigate the role of DUOX2 in preventing cancer dissemination in vivo, we next measured serum protein carbonyl content as a read out of DUOX2 activity in mice bearing stomach tumors expressing endogenous or reduced DUOX2 levels following the different treatments." (PMID 34439340, 2021). "Based on these data and the role of immune cells in inflammation we next stained the tissues with the macrophage marker CD68 to measure levels of infiltrating macrophages in gastric tumor negative or positive for DUOX2 expression." (PMID 34439340, 2021).
gastritis (3 papers, 2019 to 2021). Inflammation of the stomach. "The verification results of the GSE5081 dataset showed that except for DUOX2 and VCAM1, the other 13 genes were significantly upregulated in gastritis, which was consistent with the results in the GSE60427 dataset." (PMID 34471638, 2021). "The results showed that except for DUOX2 and VCAM1, the other 13 genes were significantly upregulated in gastritis compared to normal, which was consistent with the results in the GSE60427 dataset." (PMID 34471638, 2021). "In fact, our data indicate that six of the seven (86%) gastritis samples we examined expressed strong levels of DUOX2 in the surface of epithelial cells (data not shown)." (PMID 34439340, 2021).
prostate carcinoma (3 papers, 2017 to 2023). A carcinoma that arises from epithelial cells of the prostate gland. "DUOX2 mRNA expression has been reported to be low or undetectable in prostate cancer cell lines." (PMID 29065504, 2017).
athyreosis (2 papers, 2020 to 2022). Athyreosis is a form of thyroid dysgenesis characterized by complete absence of thyroid tissue that results in primary congenital hypothyroidism, a permanent thyroid deficiency that is present from birth. "Forty-nine of 288 children with TD carried DUOX2 variants, including 20 of 121 children with athyreosis, 14 of 93 children with ectopia and 15 of 74 children with hypoplasia, and 31 of 89 children with GIS carried DUOX2 variants." (PMID 32425884, 2020).
Cholera (2 papers, 2019 to 2022). "Dual oxidase 2 (DUOX2) and inducible nitric oxide synthase (iNOS) are both among the most upregulated proteins in duodenal tissue during cholera." (PMID 31776240, 2019). "Cholera patients’ duodenum samples at the acute phase showed more abundant NOS2 and DUOX2 transcript levels compared to the convalescent phase." (PMID 35573801, 2022).
cholestasis (2 papers, 2022 to 2023). Impairment of the bile flow caused by obstruction within the liver, or outside the liver in the bile duct system. "DUOX2 and ABCG5 play prominent roles in cholestasis which is associated with Barnesiella and Parabacteroides." (PMID 36409145, 2022). "A selective decrease in the numbers of DUOX2+ACE2+ small cholangiocytes in PBC patients significantly promoted the progression of PBC and cholestasis." (PMID 36759512, 2023).
colorectal tumor (2 papers, 2020 to 2024). "To discover underlying mechanisms by which Duox2 contributes to colorectal tumor development, we conducted RNA-Seq analysis of colon-derived RNA from Duox2 WT and CKO mice." (PMID 38659246, 2024).
glioblastoma (2 papers, 2021 to 2025). The most malignant astrocytic tumor (WHO grade IV). "Conversely, other research has found that an increase in ROS levels induced by DUOX2 can reshape the tumor microenvironment, thereby enhancing the sensitivity of glioblastoma cells to temozolomide." (PMID 40875107, 2025).
Helicobacter infection (2 papers, 2016 to 2023). "Increased DUOX2 expression may help to eradicate Hp colonization and infection as suggested by the persistent Helicobacter infection in mice deficient in DUOX2 activity." (PMID 26839536, 2016). "DUOX2-generated H2O2 limits Helicobacter infection, and the deletion of DUOX2 activity leads to increased uptake of bacterial material, resulting in a pro-inflammatory milieu within the intestinal mucosa." (PMID 37891968, 2023).
hepatic carcinoma (2 papers, 2016 to 2024). "HAND2-AS1 reverses lenvatinib resistance in hepatocellular carcinoma by promoting ferroptosis through the TLR4/NOX2/DUOX2 pathway via miR-219a-1-3p, with low HAND2-AS1 levels linked to early recurrence." (PMID 39315094, 2024). "In CRC tissues, the DUOX2 protein expression level in stages II–IV was significantly higher than that in stage I. In both hepatic carcinoma and the adjacent nonmalignant tissue, the DUOX2 was virtually undetectable." (PMID 26839536, 2016).
ileocolitis (2 papers, 2020 to 2024). Ileocolitis or ileal Crohn's is the most common type of Crohn's disease. "DUOX2 promoted the development of ileocolitis by inducing the secretion of inflammatory factors." (PMID 39224819, 2024). "Targeting DUOX2 might be a promising therapeutic method to treat ileocolitis." (PMID 39224819, 2024).
Iron deficiency anemia (2 papers, 2021 to 2024). "The DUOX2 missense variant is present in 14% of the population, associates with all iron homeostasis biomarkers, and increases the risk of iron deficiency anemia by 29%." (PMID 33536631, 2021). "Likewise, the index variant in the DUOX2 (cadmium) locus known from GWASs of iron status biomarkers, was associated with iron deficiency anemia." (PMID 38594418, 2024). "Variants at DUOX2, F5, SLC11A2 and TMPRSS6 associate with iron deficiency anemia, while variants at TF, HFE, TFR2 and TMPRSS6 associate with iron overload." (PMID 33536631, 2021).
pancreatic adenocarcinoma (2 papers, 2016 to 2022). "Although there have been in vitro studies that demonstrate the role of DUOX2 in carcinogenesis, tumor progression, and chemotherapeutic resistance, particularly in colorectal and pancreatic adenocarcinoma, the association between DUOX2 and CCRT response has rarely been reported." (PMID 36361712, 2022).
pancreatic ductal adenocarcinoma (2 papers, 2016 to 2021). An infiltrating adenocarcinoma that arises from the epithelial cells of the pancreas. "We found previously that exposure of pancreatic ductal adenocarcinoma cells to the pro-inflammatory cytokine IFN-γ increased DUOX2 expression (but not other NADPH oxidases) leading to long-lived H2O2 production." (PMID 27637085, 2016).
rectal cancer (2 papers, 2021 to 2022). A primary or metastatic malignant neoplasm that affects the rectum. "The validation of these results through IHC analysis provided preliminary confirmation that the overexpression of DUOX2 in rectal cancer is associated with treatment resistance." (PMID 36361712, 2022). "Although there is limited evidence to explain the association between DUOX2 and CCRT response in rectal cancer patients, the findings of the present study seem to agree with those of other transcriptomic studies." (PMID 36361712, 2022). "The overexpression of DUOX2 can be used as an indicator of treatment-resistant tumors and can be applied as a new ancillary tool for the management of locally advanced rectal cancer." (PMID 36361712, 2022). "Currently, a lot of previous studies have reported that genes SERPINB5, CHD4, TCN1, VNN1, EPHA4, PCSK1, and DUOX2 as prognostic biomarkers were proven to correlate with poor tumor response and survival prognosis in patients with rectal cancer receiving pCRT." (PMID 33506057, 2021). "Many studies have focused on identifying genes as biomarkers associated with tumor response and survival prognosis of rectal cancer patients with pCRT, such as SERPINB5, CHD4, TCN1, VNN1, EPHA4, PCSK1, and DUOX2 genes." (PMID 33506057, 2021). "Thus, it can be hypothesized that DUOX2-dependent oxidative stress affects treatment outcomes in rectal cancer patients treated with CCRT." (PMID 36361712, 2022). "Despite these limitations, the findings of the present study suggest that DUOX2 can be a novel biomarker for predicting non-CR after CCRT in patients with rectal cancer, highlighting the importance of the tumor microenvironment with respect to treatment responsiveness." (PMID 36361712, 2022).
acyl-CoA dehydrogenase deficiency (1 paper, 2024). "Among the top ten common variants, DUOX2, SLC22A5, PAH, and ACADS were associated with CH, primary carnitine deficiency, hyperphenylalaninemia, and short-chain acyl-CoA dehydrogenase deficiency, respectively." (PMID 38575986, 2024).
allergic rhinitis (1 paper, 2025). Inflammation of the nasal mucous membranes caused by an IgE-mediated response to external allergens. "β-glucans in HDM activate TLR2 in nasal epithelial cells to promote allergic rhinitis via DUOX2/ROS-mediated signaling." (PMID 40529570, 2025).
autoimmune hypothyroidism (1 paper, 2019).
Barrett esophagus (1 paper, 2016). Esophageal lesion lined with columnar metaplastic epithelium which is flat or villiform. "A low level of DUOX2 mRNA was found in both Barrett esophagus and the adjacent normal esophageal epithelium." (PMID 26839536, 2016). "In this study, a low level of DUOX2 mRNA was found in both normal esophagus and columnar epithelium of Barrett esophagus, although a low level of DUOX2 protein was only observed in Barrett esophagus but not normal esophagus." (PMID 26839536, 2016). "DUOX2 protein was found in Barrett esophagus and undetectable in the normal epithelium." (PMID 26839536, 2016). "Our results show the presence of DUOX2 protein in Barrett esophagus but not in normal esophagus suggesting that DUOX2 may be involved in the carcinogenesis process of Barrett esophagus via ROS production." (PMID 26839536, 2016).
brain tumors (1 paper, 2013). "Duox2 was expressed at elevated levels in many human cancers, most notably tumors of the prostate, lung, colon and breast while brain tumors and lymphomas demonstrated the lowest frequency of expression." (PMID 23404210, 2013).
breast carcinoma (1 paper, 2021). "As GALNTL5, MLIP, HMCN2, LRRN4CL and DUOX2 were identified as cytotoxicity-associated genes, we next investigated their effects on therapeutic response by analyzing RNA-seq data and drug sensitivity of multiple breast cancer cell lines using Pearson coefficient analysis." (PMID 35046993, 2021). "DUOX1 has been involved in breast cancer, whereas the role of DUOX2 on breast cancer is still unreported." (PMID 35046993, 2021). "(F-J) Survival analysis was performed for GALNTL5, MLIP, HMCN2, LRRN4CL and DUOX2 using log-rank test for RNA-seq data and the corresponding survival data from the TCGA cohort of patients with breast cancer." (PMID 35046993, 2021).
celiac disease (1 paper, 2021). An autoimmune genetic disorder with an unknown pattern of inheritance that primarily affects the digestive tract. "Although there was some LCN2 stain detected also in celiac disease, DUOX2 staining was specific to the EED cases, and no LCN2 and DUOX2 was detected in controls." (PMID 33524399, 2021).
cervical cancer (1 paper, 2019). A primary or metastatic malignant neoplasm involving the cervix. "Dual Oxidase1 (DUOX1) and Dual Oxidase 2 (DUOX2) mRNA levels were upregulated 57.9- and 67.5-fold, respectively, in cervical cancer patients." (PMID 31706280, 2019). "DUOX1 and DUOX2 were also the most abundant NOX transcripts in cervical cancer patients, whereas NOX3 was the least abundant and was undetectable in normal control subjects." (PMID 31706280, 2019). "Moreover, we analyzed the protein expression of NOX2, DUOX1, and DUOX2 using clinical tissue samples from cervical cancer patients." (PMID 31706280, 2019). "In cervical cancer patients with HPV infection, DUOX1 and DUOX2 mRNA levels were significantly increased as compared to patients without HPV infection." (PMID 31706280, 2019). "DUOX1, DUOX2, and NOX2 protein expression were also identified in our clinical cervical cancer samples." (PMID 31706280, 2019). "In this study, the increased mRNA levels of DUOX1, DUOX2, and NOX2 in cervical cancer were identified in TCGA and GEO databases." (PMID 31706280, 2019).
cervical squamous cell carcinoma (1 paper, 2019). A squamous cell carcinoma arising from the cervical epithelium. "DUOX1 and DUOX2 protein expression were also identified in cervical squamous cell carcinoma." (PMID 31706280, 2019). "In addition, mRNA and protein levels of DUOX1 and DUOX2 were higher in patients with cervical squamous cell carcinoma than in those with endocervical adenocarcinoma." (PMID 31706280, 2019). "The protein expression of DUOX1, DUOX2, and NOX2 also identified in cervical squamous cell carcinoma tissues." (PMID 31706280, 2019).
cholangitis (1 paper, 2023). An acute or chronic inflammatory process affecting the biliary tract. "Furthermore, the decreased numbers of DUOX2+ACE2+ small cholangiocytes were significantly associated with the severity of PBC, including higher Nakanuma stages, Ludwing stages, fibrosis scores, bile duct loss scores, and cholangitis activity grades." (PMID 36759512, 2023).
chronic obstructive pulmonary disease (1 paper, 2018). A chronic and progressive lung disorder characterized by the loss of elasticity of the bronchial tree and the air sacs, destruction of the air sacs wall, thickening of the bronchial wall, and mucous accumulation in the bronchial tree. "Patients with chronic obstructive pulmonary disease (COPD) have increased the susceptibility to HRV and HRV-infected airway epithelial cells from COPD patients show elevated levels of Duox1 and Duox2." (PMID 30049972, 2018).
Crohn ileitis (1 paper, 2020). A Crohn disease involving a pathogenic inflammatory response in the ileum. "Oxidant generation in IBD is usually ascribed to ER stress in Paneth cells, NOX2 in macrophages and mitochondria, although DUOX2 mRNA levels are elevated up to 20 times in active Crohn's ileitis and ulcerative colitis." (PMID 32810389, 2020). "Our hypothesis for linking microbiota to ileitis was based on the idea that Lactobacillus‐induced NOX1 oxidant generation produces damage on its own, which DUOX2 augments." (PMID 32810389, 2020).
differentiated thyroid carcinoma (1 paper, 2019). Differentiated thyroid carcinoma (DTC), also known as papillary or follicular thyroid carcinoma, is a slow-growing malignancy usually presenting in adults as an asymptomatic thyroid mass. "The prevalent physiologic function of DUOX2 in the thyroid is suggested by data demonstrating unchanged or marginally diminished DUOX2 expression in differentiated thyroid carcinomas." (PMID 31083324, 2019).
dry eye (1 paper, 2021). "We assumed that future studies are needed to clarify the pathological connection between DUOX2 oxidative signaling and these biological procedures in dry eye development." (PMID 35096875, 2021). "Though HMGB1 expression was found to be enhanced by dry eye conditions, the crosstalk between DUOX2-mediated excessive ROS release and HMGB1 during DED inflammation progression has not been previously investigated." (PMID 35096875, 2021).
ectopic thyroid (1 paper, 2020). "Recently, One study has shown DUOX2 mutations associated with CH with ectopic thyroid." (PMID 32425884, 2020).
enteritis (1 paper, 2025). Inflammation of the small intestine. "The experimental data revealed good discrimination for DUOX2, LCN2, and DEFA6 in normal individuals, enteritis patients, and IBD patients." (PMID 40830794, 2025).
fibrosis (1 paper, 2019). the formation of excess fibrous connective tissue in an organ or tissue in a reparative or reactive process. "In the lung, it has been shown that some pro-oxidant enzymes such as NADPH oxidase-1 (NOX1), NOX2, NOX4, as well as Duox1 and Duox2 are involved in oxidative stress and development of fibrosis." (PMID 31366142, 2019).